IGF2BP2 (insulin like growth factor 2 mRNA binding protein 2)
Diseases named in the same sentence as IGF2BP2 in open-access papers (continued):
Sharing a sentence is not in itself a finding about the gene and the disease.
tumor (continued). "Notably, in renal cell carcinoma, METTL14 and IGF2BP2 collaboratively regulate tumor angiogenesis and metastasis while also managing drug resistance in cancer cells during clinical treatment." (PMID 39295872, 2024). "The IGF2BP2 knockdown group had significantly slower tumor growth than the control group." (PMID 37983610, 2024). "IGF2BP2 knockdown suppressed BCa cell growth and metastasis, as well as inhibited BCa tumor growth." (PMID 39014364, 2024). "The results suggested that tumor volume and weight were markedly reduced in sh-IGF2BP2 group." (PMID 39014364, 2024). "To further confirm the pro-tumor role of IGF2BP2 in BCa, we performed xenograft tumor experiments." (PMID 39014364, 2024). "IGF2BP2 plays a critical role in promoting tumor cell proliferation by regulating the cell cycle." (PMID 39596216, 2024). "In summary, these findings indicate that tumor cells with high IGF2BP2 expression recruit both M2‐like and SPP1+ macrophages, which together may contribute to an immunosuppressive microenvironment and affect treatment outcomes." (PMID 39711402, 2024). "Also, the positive cells of IGF2BP2, proliferation marker Ki-67 and metastasis marker E-cadherin were decreased in the tumor tissues of sh-IGF2BP2 group." (PMID 39014364, 2024). "Consequently, IGF2BP2 significantly influences tumor growth, progression, and resistance to therapies." (PMID 39596216, 2024). "Given the multifaceted role of IGF2BP2 in cancer, targeting this protein could disrupt the pathological processes that support tumor growth and survival." (PMID 39596216, 2024). "In the following sections, we will review the role of IGF2BP2 in modulating tumor RNA." (PMID 39596216, 2024). "Studies have shown that IGF2BP2 is overexpressed in many cancers, correlates with progression, and promotes cancer cell proliferation and migration, while we and others have reported that circHIPK3 is downregulated in BC and possess tumor suppressor functions." (PMID 39041323, 2024). "Additionally, methylated RNA immunoprecipitation sequencing (MeRIP-seq) was conducted to identify the potential mRNAs regulated by IGF2BP2, an N6-methyladenosine (m6A) regulator, in the tumor tissues of mice." (PMID 39731162, 2024). "In this, we determined that IGF2BP2 was highly expressed in BCa, and its knockdown could inhibit BCa cell growth and metastasis, as well as tumor growth." (PMID 39014364, 2024). "IGF2BP2, an m6A ‘reader’ protein, plays a critical role in mRNA stability and tumor progression." (PMID 39080693, 2024). "Targeting IGF2BP2 could disrupt the metabolic state of tumor cells and the tumor microenvironment, thereby inhibiting tumor growth." (PMID 39596216, 2024). "Xenograft tumor model was conducted to evaluate the role of IGF2BP2 in vivo." (PMID 39014364, 2024). "Similarly, in CRC, IGF2BP2 binds to YAP mRNA to promote its translation, and verteporfin reduces the number of cancer-associated fibroblasts, inhibiting angiogenesis and tumor progression." (PMID 39098905, 2024). "The staining index of IGF2BP2 was significantly higher in tumor tissues." (PMID 39550498, 2024). "In the TCGA‐BLCA cohort, patients with high IGF2BP2 expression exhibited significantly poorer overall survival (p = 0.014) and higher expression in high‐grade tumors (p = 3.9e‐06), linking it to tumor aggressiveness." (PMID 39711402, 2024). "In the following sections, we will first introduce IGF2BP2’s function in tumor RNA regulation." (PMID 39596216, 2024). "Then we asked if there is a change in expression of IGF2BP2 targets in tumor versus normal tissues." (PMID 37248468, 2023). "Taken together, we elucidated that IGF2BP2 can promote tumor proliferation and iron metabolism." (PMID 37088822, 2023). "The mRNA expression levels of YTHDC2, YTHDF1, YTHDF3, IGF2BP1, and IGF2BP3 were significantly increased in tumour tissues compared with paired normal breast tissues, while the METTL14, WTAP, FTO, and IGF2BP2 expression levels were significantly decreased in tumour tissues." (PMID 36632454, 2023).
tumor (continued). "IGF2BP2 plays a carcinogenic role, promoting tumor formation in vivo." (PMID 35908253, 2023). "IGF2BP2 also gradually increased with increasing HPSCC tumor grade." (PMID 37612282, 2023). "In particular, IGF2BP2 promotes the proliferation of tumor cells." (PMID 37088822, 2023). "Moreover, the knockdown of CSF2 and IGF2BP2 in GC-MSCs significantly slowed the rate of tumor growth relative to GC-MSCs group." (PMID 37865637, 2023). "However, the tumor-promoting effects were attenuated upon the ablation of CSF2 in IGF2BP2 overexpression MSCs." (PMID 37865637, 2023). "Furthermore, after down-regulating IGF2BP2, IHC staining of mouse tumor tissue sections with the TFRC antibody revealed that TFRC expression decreased after IGF2BP2 was down-regulated." (PMID 37088822, 2023). "In addition, the sh-IGF2BP2 group showed a significantly slower tumor growth rate than the sh-NC group (P < 0.05)." (PMID 37936610, 2023). "IGF2BP2, which may be controlled by miR-150, seems to be involved with maintenance of cancer stem cells, and consequently with chemoresistance and tumor recurrence." (PMID 36936170, 2023). "The results showed that the expression of IGF2BP2 was significantly positively correlated with tumor purity (cor=0.113, P=1.19e-02), and was significantly negatively correlated with the infiltration levels of B cells (cor=-0.249, P=3.89e-08) and CD8+ T cells (cor=-0.225, P=1.91e-08)." (PMID 36793593, 2023). "CircEYA3, which was prominently localized in the cytoplasm, decreased tumor radiosensitivity by stabilizing deltex E3 ubiquitin ligase 3L (DTX3L) mRNA via its interaction with insulin-like growth factor 2 mRNA-binding protein 2 (IGF2BP2)." (PMID 38042777, 2023). "IGF2BP2 knockout mice experiments also confirmed its promotion of tumor development." (PMID 35129592, 2022). "Target binding of miRNAs to IGF2BP2 inhibits its expression and malignant tumor progression." (PMID 35299748, 2022). "Moreover, the results of mRNA and protein expression analysis of clinical samples showed that the expression of IGF2BP2 was significantly higher in OSCC tumor samples than in non-tumor samples." (PMID 35129592, 2022). "Functional experiments showed that loss of IGF2BP2 reduces HCC proliferation and tumor growth." (PMID 35462896, 2022). "Moreover, the expression of IGF2BP2 was significantly upregulated in tumor tissues compared with that in adjacent tissues and was positively correlated with CC stage." (PMID 35002506, 2022). "Therefore, the present study has revealed the potential role of IGF2BP2 in tumor immunology and its prognostic value." (PMID 35129592, 2022). "IGF2BP2 is an RNA‐binding protein involved in tumour progression." (PMID 35876041, 2022). "According to the TCGA database, IGF2BP2 was higher expressed in CRC tumor tissues." (PMID 36230970, 2022). "In addition, the study found that IGF2BP2 and its co-expressed genes (HMGA2, PHLDB2, and YEATS2) are all associated with a variety of TICs in OSCC tumor samples." (PMID 35129592, 2022). "That is to say, IGF2BP2 can modulate tumor development via its interaction with RNA." (PMID 35014946, 2022). "In conclusion, these results indicated that IGF2BP2 expression might lead to poor prognosis of HNSC patients by suppressing tumor immune infiltration." (PMID 36281789, 2022). "We hypothesized that mRNA vaccines targeting MMP9 and IGF2BP2 could induce immune infiltration in the tumor microenvironment of patients with immunologically “suppressive” BIS1 and BIS2 tumors." (PMID 36569935, 2022). "Finally, we explored MMP9 and IGF2BP2 expression levels in the three subtypes and found that the two potential tumor antigens were lowest in BIS3 and highest in BIS2 (Kruskal-Wallis test, P< 0.001)." (PMID 36569935, 2022). "In functional analysis, IGF2BP2 was negatively correlated to tumor immune infiltration in HNSC." (PMID 36281789, 2022).
tumor (continued). "Additionally, IGF2BP2 was found to be evidently downregulated in RCC tumour samples (523 samples) compared with normal samples (100 samples) from TCGA database." (PMID 35678231, 2022). "Finally, TIMER and CIBERSORT were used to analyze the correlations among IGF2BP2, IGF2BP2-coexpressed genes, and tumor-infiltrating immune cells (TICs)." (PMID 35129592, 2022). "The results of GSEA and tumor-infiltrating immune cell analysis indicated that IGF2BP2 might promote the malignant progression of OSCC by affecting cancer-related and immune-related biological functions and pathways." (PMID 35299748, 2022). "IGF2BP2 was correlated with tumor size (p = 0.023), and status of 131I uptake (p = 0.015)." (PMID 35267576, 2022). "IGF2BP2 has been shown to promote tumor growth in cases of solid tumors and leukemia 22-27." (PMID 35919812, 2022). "Four m5C/m6A-related gene signatures consisting of HNRNPA2B1, IGF2BP2, NSUN4, and ALYREF were used to construct a prognostic risk model, and the high-risk group had a worse prognosis, higher immune checkpoint expression, and tumor mutational burden (TMB)." (PMID 36246622, 2022). "All these results suggested that IGF2BP2 is an important tumor marker that is highly expressed in ESCC in either cells or tumor tissue, implying that it may be a potential target for ESCC imaging." (PMID 36364436, 2022). "It was found that tumor weight in IGF2BP2 knockdown group was lower than that in control group." (PMID 34630126, 2021). "IGF2BP2 was shown to act as a reader on the N6-methyladenosine (m6a) to modulate tumor progression." (PMID 34830370, 2021). "Moreover, IGF2BP2 expression was positively correlated with MTA1 expression in 78 CRC tumor tissues from the independent SYSUCC cohort." (PMID 34218271, 2021). "IGF2BP2 is a type of RBP that plays an important role in tumor development." (PMID 33824282, 2021). "The results suggest that expression of ALKBH5, IGF2BP2, METTL16, AL513165.1, and AP005233.2 is significantly associated with tumor stage and that expression of UCA1, IGF2BP2, METTL16, AL513165.1, AP005233.2, and AC099850.3 is significantly associated with tumor grade." (PMID 34233576, 2021). "Finally, analysis of our 46 pairs of CRC tumor tissues qRT-PCR showed that IGF2BP2 was higher in CRC tissues than in matched normal tissues." (PMID 34809621, 2021). "IGF2BP2 appears to promote tumor progression in PDAC and GBC." (PMID 33952279, 2021). "Conversely, IGF2BP2 knockdown repressed tumor growth in nude mice." (PMID 35111811, 2021). "OIP5-AS1 overexpression rescued the tumor suppressor effect after IGF2BP2 knockdown." (PMID 34345216, 2021). "The relationship between IGF2BP2 and tumor immune infiltration remains to be determined." (PMID 35011587, 2021). "Furthermore, IHC staining analysis indicated that the level of Ki67 was lower in IGF2BP2 knockdown crizotinib-resistant NSCLC tumor tissues compared with control tumor tissue, while tunel-positive cells were increased." (PMID 34630126, 2021). "Hmga2 is a driver of tumor metastasis and Igf2bp2 is a downstream target gene." (PMID 32793490, 2020). "We found that IGF2BP2 expression was significantly higher in tumor tissues (p < 0.001)." (PMID 32784624, 2020). "It has been reported that miR-138 may function as a tumor inhibitor by directly inhibiting IGF2BP2 and suppressing EMT during the progression of LGG." (PMID 33323543, 2020). "Then, we verified the level of IGF2BP2 protein expression in 36 pairs of HNSCC tumor tissues and adjacent tissues by immunohistochemistry staining and found significant elevated IGF2BP2 expression in terms of density and intensity in HNSCC tumor tissues compared with adjacent tissues." (PMID 32391379, 2020). "Our results demonstrate that IGF2BP2 plays an important role in tumor progression and may serve as an important biological prognostic factor for HNSCC." (PMID 32391379, 2020). "We separated the tumor group of GSE 14520 into two groups based on the median IGF2BP2 expression." (PMID 31861402, 2019).
tumor (continued). "Moreover, IGF2BP2 expression was significantly higher in the tumor tissues from these patients compared with the matched normal tissues." (PMID 31791342, 2019). "However, IGF2BP2 expression was lost in all endometrioid cases, by 25% to >95% of tumor cell populations." (PMID 29736175, 2018). "In HCC, miRNA-216b could function as a tumor suppressor by targeting IGF2BP2 and subsequently suppressing the downstream IGF2." (PMID 26989293, 2016). "Moreover, western blotting and IHC showed that expression levels of HBx and IGF2BP2 in tumor tissues were much higher than those in the adjacent liver tissues." (PMID 25741595, 2015). "Second, the field needs systematic testing whether targeting specific m6A nodes (e.g., YTHDF2 in TAMs or IGF2BP2/3 at the tumor–endothelium interface) leads to vessel normalization and improved antigen trafficking—alone or combined with anti-VEGF and checkpoint blockade." (PMID 41280938, 2025). "Bioinformatic analyses revealed that through METTL3 and IGF2BP2, circQSOX1 was upregulated and sponged with miR-326 and miR-330-5p to promote PGAM1 expression, which further activated glycolysis and cytotoxic T-lymphocyte-associated antigen-4 (CTLA-4) expression, contributing to tumor immune escape." (PMID 41373022, 2025). "Furthermore, previous studies had shown that miR-98-5p could target IGF2BP1 and IGF2BP2 to regulate tumor cell growth." (PMID 40530014, 2025). "Consistently, the in vivo subcutaneous tumor model demonstrated that FBW7 overexpression and IGF2BP2 knockdown could inhibit tumor growth and enhance the antitumor effect of IR, with the best effects obtained by combining FBW7 overexpression and IGF2BP2 knockdown." (PMID 38281999, 2024). "Additionally, IGF2BP2’s involvement in metabolic reprogramming, specifically in glycolysis and amino acid metabolism, aids cancer cells in adapting to metabolic stress, thus promoting tumor growth." (PMID 39596216, 2024). "Therefore, targeting IGF2BP2 could improve the sensitivity of tumors to these treatments, potentially overcoming resistance and enhancing the effectiveness of anti-tumor therapies." (PMID 39596216, 2024). "Hence, IGF2BP2 is a crucial tumor-promoting factor in the development of CRC, according to studies." (PMID 37828232, 2023). "Additionally, IGF2BP2 is expressed in multiple normal organs, which reduces tumor specificity." (PMID 37280679, 2023). "Therefore, in order to explore the regulation of IGF2BP2 on tumor metastasis, we further examined the expression of EMT markers and found that oe-IGF2BP2 could promote EMT process, while si-IGF2BP2 had the opposite effect (P < 0.05)." (PMID 37060505, 2023). "Current studies have shown that IGF2BP2 could participate in various tumor processes including AML." (PMID 37060505, 2023). "Multiple mechanisms may account for the role of IGF2BP2 in tumor progression." (PMID 35299748, 2022). "Synergistically, IGF2BP2 may be involved in inhibiting tumour migration induced by circ‐TNPO3." (PMID 35876041, 2022). "However, a recent study through a systematic screen for homozygous deletions of 12 human tumours, including RCC, suggests that IGF2BP2 may be a potential tumour suppressor gene." (PMID 35876041, 2022). "Moreover, the IGF2BP2 expression was found to be correlated with tumor size." (PMID 33224879, 2020). "However, miR-141 re-expression partially blocked the tumor-promoting effect of IGF2BP2." (PMID 31852504, 2019). "In summary, our study suggests that in patients with HCC, miR-216b, which could be transcriptionally reduced by HBx, functions as a tumor suppressor by targeting IGF2BP2 and subsequently suppressing the downstream IGF2, AKT/mTOR and MAPK/ERK signaling pathways." (PMID 25741595, 2015). "This revealed IGF2BP2 as a critical genetic dependency that, when targeted, downregulated PLK1 and significantly restricted tumor growth." (PMID 40347943, 2025).
tumor (continued). "In this study, we present novel insights that IGF2BP2 is essential for EGFR and PIK3R1 mRNA stability and activation of the EGFR/PI3K/AKT axis in OSCC tumor cells and CAFs." (PMID 40362183, 2025). "In this study, ZFP14 was identified for the first time not only as a tumour suppressor in ccRCC but also as a crucial target of METTL14‐mediated m6A, with IGF2BP2 participating." (PMID 39936533, 2025). "Concordantly, tumours from the LDHA group exhibited up‐regulated protein levels of Pan‐Kla, H3K18la, IGF2BP2, Nrf2 and GPX4." (PMID 41399129, 2025). "Functional studies demonstrate that PRMT1 regulates IGF2BP2 expression, which in turn mediates PRMT1‐driven oncogenic effects, including tumor proliferation, apoptosis resistance, and CBP sensitivity." (PMID 40270464, 2025). "Suppression of FTO significantly stabilizes apolipoprotein E (APOE) mRNA and coordinates with IGF2BP2, leading to the promotion of GLUT1 expression and tumor glycolysis by modulating the IL-6/JAK2/STAT3 signaling pathway." (PMID 41373022, 2025). "IGF2BP2, a classical RBP, has been shown in multiple studies to play a role in regulating mRNA stability, thereby affecting tumor progression." (PMID 40697388, 2025). "The results showed that IGF2BP2, PLAU, and CEP55 were found to be statistically significantly higher expressed in tumours than in normal samples, while CMYA5 was statistically significantly lower expressed in tumours." (PMID 40762677, 2025). "Conversely, regulators such as IGF2BP2, METTL16, and FTO demonstrated highly context-specific and sparse expression across tumor types." (PMID 40565233, 2025). "Microarray analysis revealed that IGF2BP1 and IGF2BP2, both known to stabilize mRNA, were upregulated in HBL tumor samples, and their expression correlated with ADAM32 levels." (PMID 40507253, 2025). "We found that IGF2BP2 depletion significantly inhibited HCC growth, as reflected by reduced tumor volume and tumor weight." (PMID 40900809, 2025). "Expression overlays of six RNA modification genes selected by the LASSO Cox model (DNMT1, DNMT3A, HNRNPC, IGF2BP2, NSUN5, and ZC3H13) demonstrated variable distribution across the tumor microenvironment." (PMID 40565233, 2025). "Through a combination of RNA sequencing and MeRIP-sequencing, we identified numerous altered genes and confirmed that IGF2BP2 enhances G6PD mRNA stability after METTL14-mediated m6A modification, thereby promoting tumor growth and metastasis." (PMID 39138186, 2024). "Research has shown that m6A readers such as IGF2BP2, IGF2BP3, YTHDF2, and YTHDF3 are involved in tumor angiogenesis, further influencing the occurrence and development of tumors and potentially affecting the prognosis of patients with tumors to some extent." (PMID 39295872, 2024). "In CRC, IGF2BP2 binds to the coding sequence (CDS) of SOX2, promoting tumor progression through a mechanism dependent on METTL3." (PMID 39596216, 2024). "IGF2BP1 expression was low in both normal esophageal tissue and tumor tissue, while IGF2BP2 and IGF2BP3 expression was higher in tumor tissue than in normal esophageal tissue." (PMID 38724996, 2024). "In various preclinical models of colorectal cancer (CRC), IGF2BP2 was identified as the most prevalent IGF2BP family member in both primary and metastatic CRC, showing a correlation with tumor stage in patient samples and promoting tumor growth." (PMID 39596216, 2024). "Meanwhile, FTO inhibits the expression of APOE via IGF2BP2-mediated m6A modification and regulates IL-6/JAK2/STAT3 signaling pathway to inhibit the glycolytic metabolism of PTC, thereby repressing tumor growth." (PMID 39403369, 2024). "Studies have also elucidated that LINRIS inhibits IGF2BP2 degradation in CRC HCT116 cells by inhibiting K139 ubiquitination, thereby promoting downstream MYC‐mediated glycolysis and tumor proliferation." (PMID 38721006, 2024).